TRIM28 (tripartite motif containing 28)
Diseases named in the same sentence as TRIM28 in open-access papers (continued):
Sharing a sentence is not in itself a finding about the gene and the disease.
viral infection (20 papers, 2008 to 2026). "Phosphorylation of TRIM28 plays a crucial role in regulating viral infections and their associated processes." (PMID 40421416, 2025). "The precise triggers and consequent mechanisms by which some viral infections lead to loss of SUMO-modified TRIM28 remain largely unclear, which currently limits detailed molecular studies during paramyxovirus infections." (PMID 40920817, 2025). "The precise molecular pathways by which some virus infections (particularly IAV) trigger loss of SUMO-modified TRIM28 and lead to derepression of EREs with potentiation of immune activation remain poorly understood." (PMID 40920817, 2025). "Viral infection predominantly triggered CRM1-dependent nuclear export of TRIM28, leading to its cytoplasmic accumulation." (PMID 41953019, 2026). "Herein, we have clearly shown that UBR5 promotes K63-linked ubiquitination of TRIM28, leading to inhibition of its intramolecular SUMOylation and depression of RLR transcription following virus infection." (PMID 38278841, 2024). "However, during viral infections, phosphorylation is predominantly observed in TRIM28, with fewer reports in TRIM33." (PMID 40421416, 2025). "Next, we discuss the role of TRIM28 in other viral diseases." (PMID 39534556, 2024). "TRIM28 plays a major role in cellular defense against viral infections." (PMID 39534556, 2024). "Additionally, TRIM28 plays a significant role in viral infections by modulating the host's immune response and influencing viral replication." (PMID 39534556, 2024). "UBR5-TRIM28 may serve as a rheostat to 1) minimize steady-state RLR transcription by TRIM28, and 2) to depress the TRIM28 brake rapidly upon viral infection." (PMID 38278841, 2024). "Genetic deletion of TRIM28 via CRISPR-Cas9 editing resulted in impaired type I interferon activation upon both RNA and DNA virus challenge, corresponding with increased susceptibility to virus infections in TRIM28 knockout cells." (PMID 38495890, 2024). "Nevertheless, the involved pathways, as well as the underlying mechanisms regulating TRIM28 expression during viral infection, have not yet been resolved." (PMID 37446143, 2023). "Recent reports have demonstrated that TRIM28 could regulate protein posttranslational modification and is involved in the process of viral infection." (PMID 37446143, 2023). "Moreover, the AUC-ROC value for TRIM28 gene expression was 0.841, suggesting that the expression of this gene is commonly crucial for viral infection resolution." (PMID 36192760, 2022). "Analysis of highly infection-regulated SUMO targets led us to focus follow-up studies on the host factor tripartite motif-containing-28 (TRIM28, also known as KAP1 or TIF1β), which has recently been implicated in contributing to inflammatory cytokine production during viral infection." (PMID 31391303, 2019). "In order to elucidate the signaling cascade responsible for TRIM28 S473 phosphorylation during viral infection, we concentrated further on kinases which are reported to be involved in the expression of IFN-β and proinflammatory cytokines during HPAIV infection and are known to be activated by PKR." (PMID 30323812, 2018). "Next, our model also predicts that following viral infection miRNA-dependent repressor release from target genes enables rapid gene activation, but upon low miRNAs conditions in Dicerd/d mice, such repressors (e.g TRIM28) are overexpressed, hence the lower IFN response." (PMID 22916300, 2012). "In this review, we focus on Class VI TRIM proteins, including TRIM24, TRIM28, and TRIM33, highlighting the distinct functional attributes of their RING, B-BOX1, B-BOX2, COILED COIL, PHD, and BRD domains in viral infection." (PMID 40421416, 2025). "The interaction among TRIM24, TRIM28, and TRIM33 forms a functionally significant complex that critically regulates viral infections and other cellular processes." (PMID 40421416, 2025).
viral infection (continued). "Several epigenes previously involved in response to viral infections stood out in our protein interaction analysis, such as BRD4, TOP2A, and TRIM28." (PMID 34031419, 2021). "Using TRIM28 KO cells together with a TRIM28 construct that cannot be sumoylated, they showed that ERV and innate immune response gene signatures were enhanced during viral infection of the modified TRIM28 relative to wild-type TRIM28." (PMID 31964680, 2020). "Of interest, our own past work has revealed that TRIM28/KAP1 selectively binds IN post-translationally modified by acetylation and that, in complex with HDAC1, curtails viral infection by promoting IN deacetylation." (PMID 30804369, 2019). "Among these, several are known or suspected to be involved in defending the cell against viral infection, including TRIM5, TRIM19, TRIM25 and TRIM28." (PMID 18389077, 2008). "Cells lacking TRIM28 displayed elevated levels of the VSV encoded glycoprotein G, corresponding with increased susceptibility to viral infection compared to control cells." (PMID 38495890, 2024). "Therefore, we postulated that UBR5 mediates ubiquitination of TRIM28 that prevents TRIM28 from auto-SUMOylating and inhibiting the RLR promoters during viral infection." (PMID 38278841, 2024). "Interestingly, a recent report found viral infection could trigger TRIM28 S473 phosphorylation, through a protein kinase R (PKR) - p38 mitogen activated protein kinase (p38 MAPK) -mitogen and stress response kinase 1 (MSK1) signaling cascade, to license TRIM28 to support IFN-I activation." (PMID 38495890, 2024).
glioma (19 papers, 2016 to 2025). A benign or malignant brain and spinal cord tumor that arises from glial cells (astrocytes, oligodendrocytes, ependymal cells). "TRIM28 is markedly overexpressed in gliomas, and this overexpression is associated with decreased rates of overall and progression‐free survival." (PMID 39534556, 2024). "Tripartite motif-containing 28 (TRIM28) is associated with a poor prognosis by promoting tumor progression and the activation of autophagy in glioma." (PMID 35267457, 2022). "Moreover, studies based on a nanobody-based anti-proteome approach revealed that TRIM28 can be employed as a diagnostic marker for distinguishing glioblastomas from lower-grade gliomas." (PMID 36139694, 2022). "TRIM28 is overexpressed in glioma and was associated with poorer overall survival of patients." (PMID 32731534, 2020). "The reduced expression of miR‐491 results in elevated levels of TRIM28, consequently promoting glioma cell proliferation." (PMID 39534556, 2024). "To check the importance of TRIM28 in the glioma tumor growth-promoting functions of PITAR, we tested the ability of exogenously expressed PITAR to promote tumor growth in TRIM28-silenced cells." (PMID 39302097, 2024). "As expected, small tumors formed by U87/PITAR OE/shTRIM28 glioma cells showed reduced TRIM28 and enhanced p21 staining compared to large tumors formed by U87/PITAR OE/shNT glioma cells." (PMID 39302097, 2024). "In glioma cells, the suppression of TRIM28 results in elevated levels of P21, leading to cell cycle arrest in the G1 phase." (PMID 39534556, 2024). "In gliomas, there is a notable increase in the expression levels of TRIM28 and autophagy as the tumor grade advances." (PMID 39534556, 2024). "Downregulating the abundance of TRIM28 in tumor cells can increase the efficacy of radiotherapy, and ATM inhibitor (ATMi) drugs promote the sensitivity of glioma cells to radiotherapy by inhibiting TRIM28 phosphorylation." (PMID 39100077, 2024). "In gliomas, the expression level of TRIM28 and autophagy levels are significantly elevated with the progression of tumor grade." (PMID 36756159, 2023). "In glioma cells, down-regulation of TRIM28 increased the expression of p21 and induced cell cycle arrest in G1 phase." (PMID 36756159, 2023). "And the downregulation of miR-491 can increase the expression of TRIM28 to promote glioma cell proliferation." (PMID 36756159, 2023). "Knockdown of TRIM28 was shown to abolish glioma cell proliferation in vitro and tumor growth in vivo, further supporting an oncogenic role for TRIM28." (PMID 36139694, 2022). "Functional assays provided further evidence that TRIM28-mediated glioma cell proliferation was due to TRIM28-induced autophagy." (PMID 36139694, 2022). "TRIM28 (also known as TIF1β or KAP1) is another Group C-VI protein with important implications in gliomas." (PMID 36139694, 2022). "TRIM28 and its epigenetic role as transcriptional co-repressor has been well established in cancer, including glioma cells." (PMID 36139694, 2022). "TRIM28 is overexpressed in gliomas, and its expression inversely correlates with overall survival and progression-free survival." (PMID 36139694, 2022). "Major TGF-Beta-EMT inducing factors (RHOA, RAC1, ROCK2, CDC43 and LIMK1) and EMT transcription factors (TWIST1, SOX9, TRIM28 and SERP2) have among the highest risk scores in our glioma transcriptional model." (PMID 28916782, 2017). "Our confirmatory qPCR study showed differential gene expression levels for DPYSL2, VIM and TRIM28 in “glioma versus reference” samples." (PMID 28498803, 2017). "TRIM28 was also highly expressed in glioma when compared to non-glioma controls and its expression was positively correlated with tumor malignancy, and associated with poor overall survival (OS) and progression-free survival (PFS)." (PMID 28851455, 2017).
glioma (continued). "As far as we know, this study confirmed that miR-491 directly targets TRIM28 in modulating proliferation activity of glioma cells in vitro for the first time." (PMID 27905892, 2016). "Both in vitro and in vivo, higher expression of TRIM28 lead to a worse prognosis via promotion of the proliferation ability of glioma cells." (PMID 27905892, 2016). "Down-regulation of miR-491 lead to enhanced expression of TRIM28 and promote the proliferation of glioma cells." (PMID 27905892, 2016). "Just because the important part miR-491 plays in gliomas and its possible regulation relationship with TRIM28, we conducted further researches." (PMID 27905892, 2016). "We demonstrated a positive correlation between TRIM28 expression and glioma malignancy in a previous study." (PMID 27905892, 2016). "Over the years, TRIM28 was found to be amplified in most human cancers, and increased TRIM28 expression correlates with poor patient prognosis in multiple tumor types, including ovarian, lung, glioma, and prostate." (PMID 40519166, 2025). "Evidence indicates that TRIM28 activates autophagy and enhances cell proliferation in glioma." (PMID 39534556, 2024). "Studies of two decades ago, had already provided key evidence for the role of TRIM28 in gliomas." (PMID 36139694, 2022). "Recently, transcription factor TRIM28 has been identified as a GB biomarker and, in this study, we have shown high expression of TRIM28 in GB and in low grade gliomas as well as higher expression in GSCs vs. differentiated GB cells, although in both cases not significant." (PMID 34500575, 2021). "Also, TRIM28 has been certified to be vital for activating autophagy and promoting cell proliferation in glioma." (PMID 33817325, 2021). "Also, other researches have revealed that TRIM28 is highly expressed in various malignant tumors, such as glioma, lung cancer, and cervical cancer." (PMID 33817325, 2021). "Moreover, recent studies discovered TRIM28 as a possible tumor-class predictive biomarker, used to distinguish glioblastomas from lower grade gliomas, and from reference samples with a unique nanobody-based anti-proteome approach." (PMID 28851455, 2017). "We wondered whether TRIM28 played any role in miR-491 mediated inhibition of glioma cell proliferation." (PMID 27905892, 2016). "As a result, up-regulation of miR-491 suppressed proliferation ability of glioma cells, which could be reversed by restoration of TRIM28." (PMID 27905892, 2016). "Our previous study demonstrated that knockdown of TRIM28 in glioma cells suppressed cell proliferation, which could be partially explained by the negative correlation between TRIM28 and p21 expression in GBM patients." (PMID 27905892, 2016). "Here, we detected miR-491 and TRIM28 expression and function in glioma cells." (PMID 27905892, 2016). "miR-491 regulates glioma cells proliferation in vitro by targeting TRIM28." (PMID 27905892, 2016). "High TRIM28 expression may indicate poor prognosis in patients with glioma (Qi ZX." (PMID 39100077, 2024). "In actinomycin-treated U87 glioma cells, PITAR silencing reduced the TRIM28 mRNA half-life significantly compared with control cells (compare red line with blue line)." (PMID 39302097, 2024). "TRIM24, TRIM47, TRIM44, TRIM31, TRIM14, TRIM21, and TRIM28 have exhibited significant prognostic value regarding OS and/or PFS of glioma patients." (PMID 36139694, 2022). "Three genes (TRIM28, DPYSL2 and VIM) were able to successfully distinguish gliomas from reference samples." (PMID 28498803, 2017). "Bioinformatic analysis of genes of interest against TCGA RNA sequencing data proposed TRIM28, VIM, NAP1L1 and DPYSL2 as promising “glioma versus reference” biomarkers, and suggested CRMP1, NAP1L1, NUCL, ACTB and VIM for discrimination between GBM and LGG." (PMID 28498803, 2017).
glioma (continued). "Molecular studies have found that TRIM28 is significantly elevated in glioma samples compared to normal brain tissue and is positively correlated with tumor malignancy (Qi ZX." (PMID 39100077, 2024). "Moreover, high TRIM28 expression was significantly correlated with poor OS, DSS, PFI in glioma patients, which seemed consistent with its role of TRIM28 as a tumor activator." (PMID 37367937, 2023). "Furthermore, TRIM28 was upregulated in GBM-stem-like cells, glioma tissues and cell lines, compared to normal counterparts." (PMID 36139694, 2022). "Specifically, it is involved in the transition from G1 phase to S-phase with shRNA knockdown of TRIM28 leading to a G1 phase arrest in glioma independent of DNA damage." (PMID 32731534, 2020). "Moreover, NUCL, TRIM28, VIM, and NAP1L1 were indicated as good markers to distinguish glioma tissues from reference tissues." (PMID 28498803, 2017). "In our previous study, we found the negative correlation of p21 and TRIM28 expression in glioma cells." (PMID 27905892, 2016). "In view of the tumor suppressor role miR-491 may play in glioma and miR-491 directly targeted the 3’-UTR of TRIM28, we correlated miR-491 expression with TRIM28 level." (PMID 27905892, 2016). "The negative correlation between p21 and TRIM28 indicated in our previous study could partly explain the role TRM28 played in the activation in proliferation of glioma cells." (PMID 27905892, 2016).
prostate carcinoma (18 papers, 2016 to 2026). A carcinoma that arises from epithelial cells of the prostate gland. "Given the importance of androgen deprivation therapy in the treatment of advanced prostate cancers, we investigated the effect of combining Trim28 deletion and androgen deprivation on ERV expression." (PMID 41508128, 2026). "In this study, we investigated the effect of Trim28 deletion on the expression of ERVs using an immune competent genetically engineered mouse model for prostate cancer." (PMID 41508128, 2026). "In this study, we examined how TRIM28 mediates ERV repression in this immune competent genetically engineered mouse model of prostate cancer." (PMID 41508128, 2026). "TRIM28 overexpression amplifies androgen receptor signaling, representing a pivotal mechanism in antiandrogen deprivation therapy for prostate cancer." (PMID 39534556, 2024). "The median values are 1458 bp versus 876 bp, 886 bp versus 832 bp and 686 bp versus 807 bp for the low versus high TRIM28 group of patients with endometrial cancer, prostate cancer and ovarian cancer, respectively." (PMID 37070200, 2023). "This stratification in endometrial cancer, prostate cancer and ovarian cancer patients revealed a 3.2-, 1.9- and 2.8-fold average difference of TRIM28 mRNA expression levels, respectively, between the ‘High’ and ‘Low’ groups of patients." (PMID 37070200, 2023). "TRIM28 promoted the proliferation of prostate cancer cells and was upregulated in aggressive prostate cancer, leading to poor clinical prognosis." (PMID 33817325, 2021). "We also observed the poor prognostic value of TRIM28 in brain cancer, prostate cancer, blood cancer and renal cell carcinoma and its good prognostic value in ovarian cancer." (PMID 33091876, 2020). "In agreement with this, TRIM28 was found to be depleted from open chromatin and enriched in tumor-specific closed chromatin in prostate cancer cells." (PMID 30479348, 2018). "Our approach has yielded 11 transcription factors that show strong cancer-specific transcriptional activation of targets, including the novel candidates KAT2A and TRIM28, alongside established drivers of prostate cancer MYC, ETS1, GABP and YY1." (PMID 28592290, 2017). "Since treatment of LNCaP prostate cancer cells with the antiandrogen enzalutamide promotes the expression of transposable elements, we hypothesized that combining Trim28 deletion with androgen deprivation (castration) would increase ERV expression." (PMID 41508128, 2026). "Our study of ERV expression in an immune competent genetically engineered mouse model of prostate cancer revealed that Trim28 deletion in NPp53 prostate tumors in both hormonally intact and castrated mice resulted in increased expression of ERVs at numerous loci." (PMID 41508128, 2026). "TRIM28 regulates the E2F pathway in advanced prostate cancer." (PMID 40519166, 2025). "The expression of TRIM28 is notably elevated in castration‐resistant prostate cancers." (PMID 39534556, 2024). "Notably, previous studies have shown that CD81, METTL3, STEAP1, and TRIM28 contributed to the progression of prostate cancer." (PMID 37958805, 2023). "TRIM24 becomes stabilized in prostate cancer with SPOP mutations, through mechanisms involving TRIM28, upregulated in aggressive prostate cancer and associated with elevated TRIM24 levels: TRIM28 interacts with TRIM24 to prevent its ubiquitination and degradation by SPOP." (PMID 31366128, 2019). "In contrast, TRIM28 high-tumor cells may be favorably selected as TRIM28 overexpression enhances AR signaling, which is a key mechanism to prostate cancer resistance to androgen deprivation therapy." (PMID 30479348, 2018).